KRT7 (keratin 7)
Diseases named in the same sentence as KRT7 in open-access papers (continued):
Sharing a sentence is not in itself a finding about the gene and the disease.
cholestasis (8 papers, 2021 to 2025). Impairment of the bile flow caused by obstruction within the liver, or outside the liver in the bile duct system. "The objective was to build a novel method for automated image analysis to locate and quantify the number of cytokeratin 7 (K7)-positive hepatocytes reflecting cholestasis by applying deep learning neural networks (AI model) in a cohort of 210 liver specimens." (PMID 33957930, 2021).
endometriosis (8 papers, 2009 to 2025). The growth of functional endometrial tissue in anatomic sites outside the uterine body. "Regarding the immunoprofile of ureteral endometriosis, one study revealed a strong expression of epithelial cells for ER, PR, cytokeratin 7 (CK7), and cancer antigen 125 (CA125), in addition to cluster of differentiation 10 (CD10) expression within stroma." (PMID 26490542, 2015). "In a subset of 32 patients (13 controls and 19 women with endometriosis), PF was fixed, processed and thinlayers were prepared and stained with Papanicolaou method and with immunocytochemistry using monoclonal antibodies against cytokeratin 7(CK 7), CK 8/18, Ber-Ep4, vimentin, calretinin and CD68." (PMID 19878540, 2009).
invasive ductal carcinoma (8 papers, 2015 to 2025). "A punch biopsy was acquired from the largest scalp lesion on 15 September 2022, and showed metastatic invasive ductal carcinoma with positive ER (95%), PR (5%), cytokeratin-7 (CK-7), and GATA binding protein 3 (GATA-3)." (PMID 37198611, 2023). "Instead, cytokeratin 19 (CK19), cytokeratin 7 (CK7), and MUC 1 were slightly positive especially in the solid area, which indicated differentiation of ductal adenocarcinoma." (PMID 28114893, 2017). "Excisional biopsy of the breast revealed a diagnosis of invasive ductal carcinoma with neuroendocrine differentiation, and immunohistochemical examination was negative for cytokeratin 7, making the case unusual." (PMID 33692758, 2021). "Most of the primary ductal adenocarcinomas of breast are immunoreactive to cytokeratin 7 (CK 7 (+)) and nonreactive to cytokeratin 20 (CK 20 (−))." (PMID 25883818, 2015).
non-small cell lung carcinoma (8 papers, 2013 to 2025). A group of at least three distinct histological types of lung cancer, including non-small cell squamous cell carcinoma, adenocarcinoma, and large cell carcinoma. "High level of KRT7 in serum of patients with non-small cell lung cancer complicated with superior vena cava syndrome was associated with a poor prognosis." (PMID 34070214, 2021). "Using the Kaplan–Meier plotter dataset, we analyzed KRT7 gene expression in breast, gastric, and non-small-cell lung carcinomas." (PMID 34070214, 2021). "The combined use of antibodies TTF-1 and cytokeratin 7 (CK7) for ADC and p63 with high molecular weight keratins (CK5/6) for SCC provides a very reliable distinction between these two subtypes of non-small-cell carcinoma." (PMID 31935792, 2020). "Further, PDX tissue sections generally did not express antigens characteristic of non-small cell lung cancers, including Keratin 5, Keratin 6, Keratin 7, Keratin 14, Keratin 20, TTF1, TP63, and Napsin A." (PMID 25955027, 2015). "Due to the small size of the specimen, immunohistochemical markers were performed and revealed positive staining for cytokeratin 7 and negative for TTF-1, napsin A and p 40, which were consistent with non-small cell lung carcinoma." (PMID 33832072, 2021).
Paget disease (8 papers, 2015 to 2025). A malignant neoplasm composed of large cells with large nuclei, prominent nucleoli, and abundant pale cytoplasm (Paget cells). "Pathological examination of biopsies from the erythema suggested secondary extramammary Paget disease with positive cytokeratin-7 and -20 expressions and negative GCDFP-15 expression." (PMID 30458812, 2018).
teratoma (8 papers, 2016 to 2026). A non-seminomatous germ cell tumor characterized by the presence of various tissues which correspond to the different germinal layers (endoderm, mesoderm, and ectoderm). "Critically, cells expressing markers of trophoblast lineages (KRT7 and CGB) were detected in some regions of the teratoma." (PMID 36775869, 2023).
bladder urothelial carcinoma (7 papers, 2012 to 2023). "Their findings revealed that all instances of transitional cell carcinoma of the bladder displayed KRT7 expression, while 75% tested positive for KRT20." (PMID 38260844, 2023).
carcinoid tumor (7 papers, 2002 to 2025). A slow growing neuroendocrine tumor, composed of uniform, round, or polygonal cells having monotonous, centrally located nuclei and small nucleoli, infrequent mitoses, and no necrosis. "Immunoreactivity for chromogranin A, synaptophysin, TTF-1, and pan-cytokeratins (AE1-3 clone) was observed in carcinoid component, while glandular component was positive only for TTF-1 and cytokeratins; cytokeratin 7 was selectively expressed in the adenocarcinomatous component." (PMID 34926584, 2021). "The carcinoid tumor component was strongly positive for CD56, chromogranin and synaptophysin, weakly positive for pancytokeratin, and negative for carbonic anhydrase IX, CD99, CDX2, cytokeratin 7, cytokeratin 20 and smooth muscle actin." (PMID 19523243, 2009).
ductal carcinomas (7 papers, 2014 to 2025). "Since KRT7 staining has been proposed to be associated with high-risk tumors, FFPE tissue slides from radical prostatectomies of 16 patients with highly aggressive features (i.e., ductal carcinomas) were used and stained with rabbit monoclonal SP52-KRT7 antibody." (PMID 35406395, 2022). "We have described our experience of a very rare case of cytokeratin 7 negative breast ductal carcinoma with neuroendocrine differentiation that metastasized to the orbit and formed a solitary giant tumor initially manifesting as ocular symptoms." (PMID 33692758, 2021).
mesothelioma (7 papers, 2012 to 2023). A usually malignant and aggressive neoplasm of the mesothelium which is often associated with exposure to asbestos. "Although pankeratin and D2-40 can be positive in both malignancies, as also demonstrated in a number of our cases, calretinin, keratin 5/6, keratin 7, and WT1 are typically distinguishing mesotheliomas." (PMID 24986479, 2014).
serous ovarian cancer (7 papers, 2016 to 2025). "All serous ovarian cancers exhibit high and diffuse staining for cytokeratin-7 (CK7)." (PMID 36415372, 2022).
undifferentiated carcinoma (7 papers, 2014 to 2025). A usually aggressive malignant epithelial neoplasm composed of atypical cells which do not display evidence of glandular, squamous, or transitional cell differentiation. "CT-guided biopsy of the hepatic tumor revealed an undifferentiated carcinoma with strongly positive immunohistochemical staining for cytokeratin 7, p16, Wilms' tumor 1, and β-catenin and negative staining for leukocyte common antigen." (PMID 25181387, 2014).
adenoid cystic carcinoma (6 papers, 2013 to 2026). A malignant tumor arising from the epithelial cells. "Furthermore, statistical analysis indicated that in adenoid cystic carcinoma (ACC), glandular epithelial tumor cells frequently demonstrated positive expression of markers such as cytokeratin 7 (CK7), CD117, and epithelial membrane antigen (EMA)." (PMID 41536110, 2026).
Barrett esophagus (6 papers, 2017 to 2021). Esophageal lesion lined with columnar metaplastic epithelium which is flat or villiform. "In an in vivo model, KRT7 was found to promote the transition of basal cells into the multi-layered epithelium and Barrett’s esophagus." (PMID 32081836, 2020). "While a Cox-2 conditional knockout model has not yet been utilized in genetically engineered murine models of Barrett’s metaplasia (e.g., Krt7-CreER models), the role of Cox-2 has been examined in biopsy samples and surgically induced Barrett’s metaplasia rat models." (PMID 32235869, 2020).
cervical neoplasm (6 papers, 2012 to 2025). "Immunohistochemical analysis showed findings consistent with a primary cervical neoplasm, including positivity to keratin 7, Ca-125, CEA, and p16 and negativity to Vimentin in both endometrial and cervical biopsy, oestrogen and progesterone receptors." (PMID 22236794, 2012).
colorectal tumors (6 papers, 2012 to 2025). "Keratin 7 (K7) is a cytoskeletal intermediate filament protein not expressed in the colonic epithelium but has been reported in IBD-associated colorectal tumors." (PMID 36564440, 2022).
lobular carcinoma (6 papers, 2008 to 2025). "Immunohistochemistry showed cytokeratin-19 and oestrogen receptor, but not tireoglobulin, e-cadherin or cytokeratin-7, thereby confirming metastases from a lobular breast carcinoma." (PMID 29409458, 2018). "Immunohistochemistry revealed cytokeratin-19 and oestrogen receptor, but not tireoglobulin, e-cadherin or cytokeratin-7, thereby suggesting metastases from a lobular breast carcinoma." (PMID 29409458, 2018). "Cytokeratin 7 (CK 7), ER, PR and gross cystic disease fluid protein-15 (GCDFP-15) usually stain positive in secondary deposits of lobular carcinoma and negative in primary GI tumors." (PMID 31629292, 2019).
salivary gland tumors (6 papers, 2015 to 2025). "Hematoxylin and eosin staining revealed a salivary gland tumor with poorly differentiated, solid phenotype with low ALDH1A1 and strong CD44, HLA and keratin-7 expression." (PMID 40371051, 2025).
ampullary adenocarcinoma (5 papers, 2014 to 2025). "The ampullary adenocarcinoma cell lines MDA-AMP7, AVC1, RCB1280, SNU478 and SNU869 were grown in standard culture medium and expression of KRT7, KRT20, CDX2, E-Cadherin and ZEB1 mRNA was measured by real-time PCR." (PMID 26951071, 2016).
gastrointestinal carcinoma (5 papers, 2012 to 2020). "Additionally, liver sections housing tumors were stained with CA 19-9 or cytokeratin 7 or markers of gastrointestinal carcinoma." (PMID 33020436, 2020).
germ cell tumor (5 papers, 2018 to 2025). A benign or malignant, gonadal or extragonadal neoplasm that originates from germ cells. "IHC confirmed the diagnosis of pure ovarian choriocarcinoma, showing strong positivity for β-hCG and cytokeratin 7 (CK7) and negativity for AFP and SALL4, ruling out other germ cell tumors." (PMID 40735309, 2025).
liver diseases (5 papers, 2016 to 2024). "Cytokeratin 7(K7) is a common immunohistochemical (IHC) marker for chronic cholestasis in liver biopsies - especially in liver diseases with biliary tract inflammation." (PMID 33957930, 2021).
metanephric adenoma (5 papers, 2016 to 2025). A benign, well-circumscribed renal cortical neoplasm affecting females more often than males. "The examined markers are CD56, CD57, WT1, AMACR, KRT7, and KRTAE1/AE3, which assist to separate nephroblastoma with epithelial predominance from morphologically indistinguishable metanephric adenoma." (PMID 40177273, 2025).
thyroid neoplasms (5 papers, 2011 to 2024). "Almost all thyroidal tumor’s expression levels for KRT7 and KRT20 have been found to be positive and negative, respectively." (PMID 28117295, 2017). "While the study found a positive result for KRT7, none of the thyroid tumors or their metastases reacted at all to the KRT20 antibody." (PMID 28117295, 2017).
basal cell carcinoma (4 papers, 2009 to 2025). A carcinoma involving the basal cells. "In the skin, cytokeratin 7 may be expressed in basal cell carcinomas and trichoepitheliomas." (PMID 19466292, 2009).
colitis (4 papers, 2016 to 2022). Inflammation of the colon. "ScRNA-seq analysis also revealed that a new skin-like epithelial population called squamous neo-epithelium marked by the expression of Sox2/Krt14/Krt7 could confer the resistance to colitis injury and rebuild the epithelial structure after colitis." (PMID 36045190, 2022).
diabetes (4 papers, 2021 to 2025). "Cytokeratin-7 (CK-7) is an intermediate filament expressed in the simple epithelium and was recently found to be up-regulated in endocrine islets of Langerhans in experimental diabetes." (PMID 37189422, 2023).
invasive carcinoma (4 papers, 2017 to 2025). A carcinoma that is not confined to the epithelium, and has spread to the surrounding stroma. "Pathological examination of the biopsy indicated high-grade invasive carcinoma, most consistent with prostatic origin, as evidenced by positive immunohistochemical staining for homeobox protein Nkx-3.1 (NKX3.1), cytokeratin AE1/AE3, and cytokeratin 7 (CK7)." (PMID 40662033, 2025).
lymphoepithelioma (4 papers, 2012 to 2022). "The tumor cells were positive for cluster of differentiation (CD) 10, cytokeratin (CK) AE1/AE3, cytokeratin 7, cytokeratin 20, cytokeratin 34βE12, GATA binding protein 3 (GATA3), and protein‐63 (p63), which are markers of lymphoepithelioma‐like carcinomas." (PMID 36052737, 2022).
Pleural effusion (4 papers, 2013 to 2021). The presence of an excessive amount of fluid in the pleural cavity. "Malignant cells in the pleural effusion were positive for Cytokeratin 7 (CK7) and negative for cytokeratin 20 (CK20)." (PMID 30634950, 2019). "Extensive immunohistochemistry staining of the cell block prepared from the pleural effusion sediment in an attempt to find out tumor origin showed that the metastatic adenocarcinoma was positive for cytokeratin 7 (CK7) and negative for cytokeratin 20 (CK20)." (PMID 29729664, 2018).
primary biliary cholangitis (4 papers, 2021 to 2023). Primary biliary cholangitis (PBC) is a chronic and slowly progressive cholestatic liver disease of autoimmune etiology characterized by injury of the intrahepatic bile ducts that may eventually lead to liver failure. "Aberrant cytokeratin 7 expression by hepatocytes (CK7+Hs) is the hallmark characteristic of cholestasis diseases, especially in ductopenia diseases such as primary biliary cholangitis (PBC)." (PMID 36324070, 2022). "Aberrant cytokeratin 7 expression by hepatocytes can predict the ductopenia grade in primary biliary cholangitis." (PMID 36324070, 2022).
small intestinal tumor (4 papers, 2012 to 2024). "Immunohistochemical analysis demonstrated positivity for Cytokeratin 7 (CK7), Transcription Termination Factor 1 (TTF1) and SWI/SNF-related, matrix-associated, actin-dependent regulator of chromatin, subfamily A, member 4 (SMARCA4) in the metastatic small intestinal tumor." (PMID 39659798, 2024).
Wilms tumor (4 papers, 2022 to 2025). An embryonal neoplasm characterized by the presence of epithelial, mesenchymal, and blastema components. "The absence of WT1 expression, lack of characteristic genetic alterations and the presence of atypical KRT7 positivity raise the question of whether this tumour represents a true nephroblastoma or a morphologically similar but biologically distinct neoplasm." (PMID 40177273, 2025).
Ampullary cancer (3 papers, 2011 to 2025). "Ampullary cancer (AC) was classified as pancreatobiliary, intestinal, or other subtype based on the expression of cytokeratin 7 (CK7) and cytokeratin 20 (CK20)." (PMID 21992455, 2011).
anal tumor (3 papers, 2017 to 2019). "Immunohistochemistry revealed that both the rectal tumor and anal tumor were cytokeratin 7 (CK7) − and cytokeratin 20 (CK20) +." (PMID 31429762, 2019).
bladder (3 papers, 2008 to 2022). "Regarding the localization of KRT7 staining in benign prostatic glands, few authors have reported a similar KRT7 staining, but the staining of normal prostatic ducts has already been described as physiological." (PMID 35406395, 2022). "Some stem cell markers were found as highly expressed in AR-negative basal epithelial cells from benign prostate tissue and low in luminal tumoral cells, in a similar pattern to the one we observed for KRT7." (PMID 35406395, 2022).
eccrine porocarcinoma (3 papers, 2022 to 2025). A carcinoma with eccrine differentiation arising from the sweat glands. "The tumor cells stained strongly positive for cytokeratin 7 (CK7) and epithelial membrane antigen (EMA), and negative for androgen receptors, favoring eccrine porocarcinoma over sebaceous carcinoma." (PMID 40027430, 2025).
epithelioid mesothelioma (3 papers, 2021 to 2025). "A laparoscopic biopsy confirmed malignant epithelioid mesothelioma, supported by immunohistochemical positivity for cytokeratin 7 (CK7), calretinin, and Wilms tumor 1 (WT1)." (PMID 41246574, 2025).
inflammatory bowel disease (3 papers, 2015 to 2023). A spectrum of small and large bowel inflammatory diseases of unknown etiology.
invasive breast carcinoma (3 papers, 2018 to 2023). A carcinoma that infiltrates the breast parenchyma. "Although it is not possible to be certain from this case alone, we speculated that some such cases might involve cytokeratin 7-negative invasive breast cancer with neuroendocrine differentiation." (PMID 33692758, 2021). "Immunofluorescent staining with antibodies against α-SMA, cytokeratin-7 and TGF-ß1 showed that the red fluorescence of TGF-ß1 colocalized with green fluorescence of α-SMA, but not with cytokeratin-7 in both invasive breast carcinoma and ductal carcinoma in situ." (PMID 29325547, 2018).
malignant mesothelioma (3 papers, 2015 to 2025). A malignant neoplasm of the pleura or peritoneum, arising from mesothelial cells. "Histopathologic examination confirmed malignant mesothelioma of epithelioid type, supported by immunohistochemical reactivity for calretinin, cytokeratin 7 (CK7), cytokeratin 5/6 (CK5/6), pan-cytokeratin (PanCK), Wilms tumor 1 (WT1), and loss of BRCA1-associated protein-1 (BAP1)." (PMID 40978995, 2025). "Primaquine targets KRT7, a novel interactor of KRT5, whose high expression has been correlated with tumour aggressiveness and drug resistance in malignant mesothelioma." (PMID 33916178, 2021).
medullary carcinoma (3 papers, 2017 to 2025). "Immunohistochemical staining showed positive expression for calretinin, pancytokeratin, and cytokeratin 7, consistent with the diagnosis of medullary carcinoma." (PMID 39860304, 2025). "Histopathological examination confirmed medullary carcinoma with lymph node and liver metastases, supported by immunohistochemistry, which showed positive markers (calretinin, pancytokeratin, cytokeratin 7) and excluded other malignancies." (PMID 39860304, 2025).
small intestinal cancer (3 papers, 2019 to 2024). "Histopathology and immunohistochemistry of the uterine tumor revealed that it was a metastasis of small intestinal cancer (Cytokeratin 7 [CK7] [−], Cytokeratin 20 [CK20] [+], Special AT-Rich Sequence-Binding Protein 2 [SATB2] [+], Paired Box Gene 2 [PAX2] [−], and estrogen receptor [ER] [−])." (PMID 39156866, 2024).
triple-negative breast carcinoma (3 papers, 2020 to 2023). An invasive breast carcinoma which is negative for expression of estrogen receptor (ER), progesterone receptor (PR), and human epidermal growth factor receptor 2 (HER2). "In this study, freshly isolated triple-negative breast cancer biopsied cells obtained from consenting patients were subjected to flow cytometry and bioinformatic analysis to identify three endothelial cell subclusters: EC (ATP1B3), EC (HSPA1B), and EC (KRT7) in the tumor microenvironment." (PMID 35265720, 2022).
biliary atresia (2 papers, 2014 to 2022). A rare, biliary tract disease characterized by progressive obliterative cholangiopathy of the intra- and extrahepatic bile ducts, occurring in the embryonic/ perinatal period, leading to severe and persistent neonatal jaundice and acholic stool. "induction and duration of illness after rhesus rotavirus exposure effect on the expression of cytokeratin-7 and cytokeratin-19 mice models of biliary atresia." (PMID 36451979, 2022).